G6PD (glucose-6-phosphate dehydrogenase)
Diseases named in the same sentence as G6PD in open-access papers (continued):
Sharing a sentence is not in itself a finding about the gene and the disease.
malaria (continued). "The host-parasite co-evolutionary processes are well understood by the association of coding variations such as G6PD, Duffy blood group receptor, HLA, and beta-globin gene variants with malaria resistance." (PMID 16216127, 2005). "Here, a simple screening method is described, detecting, at molecular level and with limited costs, the most important human haemoglobin and G6PD polymorphisms associated with malaria." (PMID 16356170, 2005). "In malaria-endemic regions, individuals with deficiency may appear to have normal G6PD activity using an enzymatic test, potentially due to more rapid red blood cell turnover caused by infection." (PMID 41575919, 2026). "Furthermore, National Malaria Elimination Programmes should expand access to diagnostic kits and medicines and enforce mandatory glucose-6-phosphate dehydrogenase enzyme testing." (PMID 41639872, 2026). "Thus, G6PD deficiency offers a natural protective advantage against malaria by making red blood cells less hospitable to the parasite." (PMID 40689289, 2025). "Interestingly, glucose-6-phosphate dehydrogenase deficiency has been widely associated with resistance to malaria, although the mechanisms underlying this protective effect remain poorly understood." (PMID 40869002, 2025). "Despite concerns of severe drug-induced haemolysis in at-risk patients, point-of-care G6PD testing is often unavailable in malaria-endemic areas and most national malaria programmes recommend low total dose primaquine (3·5 mg/kg) administered during 14 days to reduce the risk of haemolysis." (PMID 37748496, 2024). "At the healthcare systems level, it could reduce the associated costs and the burden on transfusion services by reducing the number of haemolytic crises caused by PQ or TQ in individuals with unknown G6PD status and malaria treatment." (PMID 39488711, 2024). "Thus, the WHO acknowledges that two diagnoses are required towards the safe and effective radical treatment of malaria: the presence of P. vivax parasites and G6PD deficiency status." (PMID 38308253, 2024). "A joint mean regression disease mapping model could provide insights into how the mean risk of malaria is correlated with the mean risk of G6PD." (PMID 38179076, 2024). "Acute hemolytic crisis in individuals with deficient or intermediate G6PD activity is a medical problem associated with the use of primaquine and tafenoquine, the only two 8-aminoquinoline drugs approved for the radical treatment of malaria." (PMID 37967096, 2023). "A recent report suggests that malaria infection may also result in increased G6PD activity when looking across all malaria in deficient and intermediate cases." (PMID 37824592, 2023). "These variations in the prevalence rates suggest that the genes, although rare, are highly polymorphic (almost 500 variants), and clinically relevant variants may be ignored during G6PD genotyping in holoendemic malaria zones." (PMID 36959634, 2023). "Moreover, deficiency of glucose-6-phosphate dehydrogenase (G6PDD) has been reported to decrease malaria parasitaemia." (PMID 36959634, 2023). "Despite the high susceptibility and endemicity of malaria among the Orang Asli in Malaysia, there is a scarcity of molecular studies of the G6PD variants that may impede a successful radical cure of malaria infection." (PMID 38085718, 2023). "Current malaria policies usually reflect associated funding by the Global Fund, so it is unclear whether the cost-effectiveness of G6PD testing is an important driver in country-level decision making." (PMID 37242320, 2023). "All samples will be assessed using molecular techniques for known and unknown variants of the G6PD gene (Xq28) and other candidate markers related to malaria susceptibility and treatment outcomes such as alpha and beta thalassaemia, Gerbich and Ovalocytosis." (PMID 35585641, 2022). "Therefore, the idea that G6PD deficiency is a protective factor for malaria requires more research data." (PMID 36160421, 2022).
malaria (continued). "In 2022, the World Health Organization Global Malaria Programme convened a technical consultation to propose a revised classification scheme for G6PD variants, spurred on by overlapping reports of G6PD activity in Classes II and III, and scarcity of reports in Class V." (PMID 36145477, 2022). "Around 57.4% of G6PD deficient individuals and 16% of the AS were found to be malaria positive." (PMID 36384674, 2022). "Malaria patients with G6PD MahidolG487A mutation (n = 17) compared to wildtype patients without common Southeast Asian (SEA) mutations including the G6PD MahidolG487A (n = 215) exhibited a significant decrease in haemoglobin levels (11.16 ± 2.65 g/dl vs. 12.66 ± 1.92 g/dl; p = 0.041)." (PMID 36038921, 2022). "The increase in G6PD activity during malaria is probably triggered by the Plasmodium infection, the observed change in G6PD activity may alter the risk profile of standard malaria treatment with 8-aminoquinolines." (PMID 35544453, 2022). "Despite most G6PD-deficient persons being asymptomatic, haemolytic anaemia, a main clinical sign, can occur 1–3 days after exposure, after eating fava beans, or can be triggered by infections or by certain drugs, such as those used to treat malaria." (PMID 35527254, 2022). "However, the risk of haemolysis in G6PD deficient individuals hampers the widespread use of PQ safely in malaria-infected patients." (PMID 36384674, 2022). "Indeed the A-allele of G6PD-202 G > A polymorphism has been associated with protection against severe malaria in African populations, such as in Mali, the Gambia and Uganda." (PMID 35811813, 2022). "Moreover, it is understood that the relationship between G6PD and Duffy variants can modify clinical symptoms in malaria caused by P. vivax and this deserves to be further investigated and explored among this population." (PMID 35527254, 2022). "Additional molecular work to assess parasite relatedness, genetic variants of G6PD, and drug metabolism, e.g., cytochrome p450 2D6 as it relates to malaria as well as antigen and antibody testing for diseases of public health importance may be conducted." (PMID 35392979, 2022). "In this study, 66.7% (12/18) of G6PD deficient individuals were malaria positive." (PMID 36076204, 2022). "In addition, those with a G6PD deficiency are thought to have some protection against malaria, increasing the interest in developing an effective pharmacological inhibitor of G6PD for clinical use." (PMID 35213227, 2022). "In the combined sample, males were two times more likely than females to identify as G6PD deficient [13.3% (22/165) vs. 6.5% (10/155)] and more than two times more likely to be malaria-infected than females (6.87% vs. 3.12%; crude OR = 2.06; 95% CI, 1.01-4.22; p = <0.05)." (PMID 34108049, 2021). "A recent meta-analysis of 28 studies addressing the question of whether G6PD deficiency protects against malaria showed a moderate protective effect against uncomplicated falciparum malaria (OR: 0.77; 95% CI, 0.59–1.02)." (PMID 33543710, 2021). "Given that G6PD deficiency favors malaria resistance, we investigated whether it plays a role in the ECM pathological process during the P.berghei infection." (PMID 34456927, 2021). "G6PD mutations are distributed worldwide and particularly widespread in malaria endemic regions." (PMID 33413378, 2021). "This evidence directly informs the distribution of risk with G6PD screening in the context of primaquine therapy against latent malaria, and may serve to mitigate risk to G6PD heterozygotes." (PMID 34270547, 2021). "However, hemolytic toxicity in individuals with genetic deficiency of G6PD limits the use of PQ for malaria radical cure and prevents widespread use of this drug in public health." (PMID 33922294, 2021). "G6PD-deficient patients with malaria may have higher than expected G6PD enzyme activity and an attenuated risk of primaquine-induced hemolysis compared to the risk when not infected." (PMID 33891581, 2021).
malaria (continued). "Importantly for malaria treatment, the population risks associated with 8-aminoquinoline radical cure are greatly overestimated from G6PD prevalences in the healthy population." (PMID 33543710, 2021). "However, an increasing proportion of P. vivax cases among all malaria cases in the country underscores the importance of testing for G6PD deficiency at the point of care in Brazil." (PMID 34383774, 2021). "The varying degree of G6PDd detected among malaria-infected national groups by advanced diagnostic tools, strongly support the recommend G6PD testing by the National Malaria Control Program and the subsequent safe treatment of P. vivax by primaquine for radical cure." (PMID 34108049, 2021). "The differences may be explained by selective pressures in regions where malaria is/was common, as G6PD deficiency may convey resistance to malaria." (PMID 34302047, 2021). "SLD-PQ may be beneficial in mass drug administration (MDA) campaigns to prevent malaria transmission but uptake is limited by concerns of hemolysis in glucose-6-phosphate dehydrogenase (G6PD)-deficient individuals." (PMID 34627346, 2021). "As WHO recommends for G6PD testing for the safe use of primaquine, G6PD deficiency rates among malaria-infected population is of interest in order to determine whether G6PD screening is required for primaquine use." (PMID 34108049, 2021). "The design, items contained in the test packet, test cassette (or test strip), and procedures of qualitative tests for G6PD screening are similar to those of existing rapid diagnostic test (RDT) for malaria, which will facilitate the training of health personnel." (PMID 34353361, 2021). "These bioinformatics results suggest that G6pd deficiency could protect against excessive immune responses, caused by P.berghei infection, and thus suppress malaria complications." (PMID 34456927, 2021). "It has also been hypothesized that protection against severe malaria is through early phagocytosis of G6PD-deficient erythrocytes that are parasitized by P. falciparum." (PMID 33679730, 2021). "However, other selective pressures such as malaria (positive selection for G6PD polymorphism and α-3.7kb) and cultural habits such as inbreeding, surely also contributed for the selection of risk genotypes for hypertension." (PMID 35283964, 2021). "If G6PD Med is approximately at an equilibrium allele frequency in the Pashtun population (i.e. is under balancing selection), this implies that it must be harmful, i.e. malaria alone cannot create balancing selection." (PMID 33543710, 2021). "According to a molecular epidemiology survey, glucose-6-phosphate dehydrogenase (G6PD) deficiency has an anti-malaria effect and we found that the G6PD Mahidol 487G>A variant protects against uncomplicated Plasmodium vivax (P.vivax) infection and reduces disease severity in previous study." (PMID 34456927, 2021). "That hypothesis is supported by evidence of recent selection pressure at G6PD and by studies defining the effect of G6PD variation on malaria risk." (PMID 32536341, 2020). "Furthermore, through a multi-population analysis of the effect of variation at G6PD on malaria risk, we have recently demonstrated that G6PD deficiency is associated with opposing additive effects on cerebral malaria and SMA." (PMID 32536341, 2020). "We show in the current study that the co-inheritance of haemoglobin AA variations and G6PD intermediate status is associated risk of severe malaria while the carriage of the sickle cell trait and normal G6PD is associated with protection against severe malaria." (PMID 32646433, 2020). "The diagnostic and treatment components of the malaria elimination strategy will need to address not only the technical and logistical aspects of the new G6PD diagnostic tool but also challenges related to the health system, service delivery capacity, and the patient’s demands and preferences." (PMID 33396538, 2020).
malaria (continued). "According to the genotyping of 31 Tag SNPs around the G6PD A‐ allele and an additional analysis based on the 1000 Genomes Project, our results were consistent with the malaria hypothesis." (PMID 31872983, 2020). "Our findings demonstrate that glucose‐6‐phosphate dehydrogenase (G6PD) A‐ allele could reduce the risk of P. falciparum infection in the African population and indicate that malaria has a recent positive selection on G6PD A‐ allele." (PMID 31872983, 2020). "In southern Papua less than 3% of the population are G6PD deficient, a likely reflection of the high proportion of the population who are of Highland ethnicity and therefore whose ancestors will have lived in non-malaria areas." (PMID 33175835, 2020). "This possibility suggests the ‘malaria hypothesis’, which posits that G6PD‐deficient alleles have been selected at high frequencies because they exert protective effects against malarial infections." (PMID 33128437, 2020). "Therefore, it was imperative to investigate the effect of ABO, G6PD and haemoglobin variants on highland malaria in Kenyan children resident in western Kenya." (PMID 32646433, 2020). "By genotyping 33 Tag SNPs around two G6PD‐deficient alleles (Canton and Kaiping), we obtained results that were consistent with the malaria hypothesis." (PMID 33128437, 2020). "This indicated that G6PD‐deficient cells were protective against malaria." (PMID 31872983, 2020). "Our findings demonstrate G6PD A‐ allele could reduce the risk of Plasmodium falciparum infection in African population and indicate malaria has recent positive selection on G6PD A‐ allele." (PMID 31872983, 2020). "This study also demonstrated that G6PD deficiency may be protective against Plasmodium falciparum uncomplicated malaria in Africa." (PMID 30819192, 2019). "Safety, tolerability, CYP2D6 and G6PD variant data from this study support the deployment of the WHO-recommended SLD primaquine without G6PD testing in South African districts with low-intensity residual transmission aiming to eliminate malaria." (PMID 31234865, 2019). "Prevalence and distribution of G6PD variants in 252 malaria patients in Myanmar were analysed." (PMID 29548282, 2018). "Extension of research in the same areas corroborated the results and inferences of previous studies and revealed that the G6PD-deficient individuals with vivax malaria were less likely to report the occurrence of malaria episodes due to the protective effect related to the enzyme activity." (PMID 30286752, 2018). "It is also controversial in imported malaria due to all the problems related to a considerable number of individuals being mildly-to-severely G6PD deficient; the adherence to the long-duration regimen as well as limited ad-hoc availability of the drug in many European countries." (PMID 30497487, 2018). "But paradoxically, G6PD deficiency is also a stumbling block in fighting against malaria." (PMID 29548282, 2018). "Inability to maintain normal redox status in G6PD deficient RBCs results in oxidative stress that may unfavorable to malaria parasites, which supporting the protection hypothesis." (PMID 29548282, 2018). "It has been proposed that G6PD variants render males substantial protection against severe malaria." (PMID 29548282, 2018). "Additionally, the prevalence of common mutation (A376) was 4.41% (3/68) and uncommon mutation (G535A) was 4.41% (3/68) among the malaria patients in exon 5 of the G6PD gene." (PMID 30918572, 2018). "At present, the prevailing hypothesis is that G6PD deficiency confers protection from severe malaria disease caused by P. falciparum." (PMID 30286752, 2018). "Evidence for human adaptation to malaria parasites are for instance sickle‐cell and glucose‐6‐phosphate dehydrogenase deficiency (G6PD) genes in certain populations living in highly endemic malaria areas (Luzzatto, Usanga, & Reddy, 1969; Pauling, Itano, Singer, & Wells, 1949)." (PMID 29636796, 2018).
malaria (continued). "A recent paper reported G6PD genetic variants in malaria patients from Jimma zone." (PMID 30314477, 2018). "This is a major problem because G6PD deficiency is common in regions where malaria is present: in some areas up to 30% of the population may be G6PD deficient." (PMID 28155819, 2017). "Indeed, various G6PD alleles have been shown to cause a reduction in G6PD activity with differing severity, and were proposed to correlate with the malaria protection they conferred." (PMID 28751503, 2017). "For G6PD, the associations were most pronounced among female participants and for current transmission intensity (parasite prevalence) compared with historical or recent measures of malaria transmission." (PMID 28541483, 2017). "Frequency for this G6PD allele was 0.0364 in malaria-patients and 0.0200 in healthy individuals." (PMID 29065882, 2017). "Several lines of evidence indicate that the G6PD+202T allele has been under recent positive selection and the main driving force for positive selection is thought to be heterozygote advantage against malaria in females." (PMID 28067620, 2017). "The coincident distribution of G6PD deficiency and malaria leads to a practical problem since the 8-aminoquinoline primaquine, the only drug active against hypnozoites used as radical treatment of vivax malaria, can cause severe haemolysis in G6PD deficient individuals." (PMID 28356147, 2017). "However, neither application of primaquine is deployed, in large part due to uncertainties relating to safety in glucose-6-phosphate dehydrogenase deficient (G6PDd) patients (National Malaria Control Programme, Pers." (PMID 28376871, 2017). "The requirement of the G6PD enzyme in this pathway provided a rationale for explaining why G6PD-deficient infected cells are less able to survive oxidative stress and, hence, why G6PD-deficient patients are more resistant to malaria." (PMID 27502771, 2016). "Moreover, in a large case–control study in Kenyan individuals, a significant increased risk to severe malarial anaemia associated with lower haemoglobin levels in G6PD deficient children with severe malaria at the time of hospital admission was found." (PMID 27388012, 2016). "The availability of practical G6PD diagnostic devices at the periphery of healthcare delivery in the endemic tropics would meet an urgent need to provide primaquine therapy to the G6PD-normal majority infected by the relapsing malarias." (PMID 26894297, 2016). "In order to identify any possible influence of G6PD deficiency on asymptomatic malaria carriage, this study was conducted over the off peak malaria season, from February through to May 2015, when symptomatic P. falciparum carriage is low." (PMID 27456336, 2016). "So it is essential to extend G6PD deficiency study in malaria endemic areas of the country." (PMID 27880809, 2016). "However, malaria is endemic in southern parts of Bangladesh including Bandarban, Rangamati and Khagrachari and knowing the G6PD deficient status in those malaria endemic areas would help to treat malaria patients." (PMID 27880809, 2016). "First, only patients with severe malaria were included, which could explain the findings, especially as the G6PD deficient allele 202A appears to confer protection against cerebral malaria and increases the risk of severe malarial anaemia." (PMID 27388012, 2016). "In addition, genotyping studies for the exploration of G6PD variants should be conducted in malaria-endemic areas of Yemen." (PMID 27329471, 2016). "However, more information is needed on the distribution of G6PD-deficiency variants in the world, as well as more affordable tests to identify at-risk individuals, particularly in malaria-endemic countries." (PMID 26753754, 2016). "Even if Mexico, Haiti, and Costa Rica would have eliminated malaria, other countries are still in control phase and require the use of primaquine knowing the risk of haemolysis that may result in G6PD-deficient persons." (PMID 27267757, 2016).